SPG7 (SPG7 matrix AAA peptidase subunit, paraplegin)
Description:
Catalytic component of the m-AAA protease, a protease that plays a key role in proteostasis of inner mitochondrial membrane proteins, and which is essential for axonal and neuron development. SPG7 possesses both ATPase and protease activities: the ATPase activity is required to unfold substrates, threading them into the internal proteolytic cavity for hydrolysis into small peptide fragments (By similarity). The m-AAA protease exerts a dual role in the mitochondrial inner membrane: it mediates the processing of specific regulatory proteins and ensures protein quality control by degrading misfolded polypeptides (By similarity). Mediates protein maturation of the mitochondrial ribosomal subunit MRPL32/bL32m by catalyzing the cleavage of the presequence of MRPL32/bL32m prior to assembly into the mitochondrial ribosome (By similarity). Acts as a regulator of calcium in neurons by mediating degradation of SMDT1/EMRE before its assembly with the uniporter complex, limiting the availability of SMDT1/EMRE for MCU assembly and promoting efficient assembly of gatekeeper subunits with MCU. Also regulates mitochondrial calcium by catalyzing degradation of MCU. Plays a role in the formation and regulation of the mitochondrial permeability transition pore (mPTP) and its proteolytic activity is dispensable for this function.
Synonyms: CAR; CMAR; PGN; SPG5C; LOC101930112
Tractability: Small molecule: a structure with a bound ligand is known; it has a binding pocket of medium quality. Antibody: UniProt predicts a signal peptide or a membrane-spanning region. PROTAC: ubiquitination databases record sites on it; its protein half-life has been measured.
Safety:
Unwanted effects reported when the protein is acted on. In parentheses: how it was acted on, where the effect was seen, and who reports it.
cardiotoxicity (source: ClinPGx)
drug toxicity (source: ClinPGx)
Gene: Protein-coding gene on chromosome 16 (89,490,719 to 89,557,766, forward strand). Ensembl gene ENSG00000197912.
Subcellular location: Mitochondrion inner membrane
Pathways (Reactome):
Metabolism of proteins: Mitochondrial protein degradation
Transport of small molecules: Processing of SMDT1
Gene Ontology:
Molecular function: metalloendopeptidase activity; protein binding; ATP hydrolysis activity; peptidase activity; ATP binding; ATP-dependent peptidase activity; zinc ion binding
Biological process: mitochondrial outer membrane permeabilization involved in programmed cell death; mitochondrial protein processing; regulation of calcium import into the mitochondrion; regulation of mitochondrial membrane permeability; nervous system development; proteolysis
Cellular component: m-AAA complex; mitochondrial inner membrane; mitochondrial permeability transition pore complex; mitochondrion; membrane
Genetic constraint (gnomAD): Loss-of-function variants: 93 observed, 71.42 expected, observed/expected ratio (o/e) 1.3, 90% interval 1.1 to 1.55. The upper end of that interval is the gene's LOEUF score, 1.55, which puts it in group 6 of 6, group 1 being the genes least tolerant of losing a copy. Missense variants: 1,214 observed, 1,079.2 expected, observed/expected ratio (o/e) 1.12, 90% interval 1.07 to 1.18. Synonymous variants: 526 observed, 448.18 expected, observed/expected ratio (o/e) 1.17, 90% interval 1.09 to 1.26.
Gene-disease validity (ClinGen):
ClinGen rates the evidence that SPG7 causes each of these diseases.
mitochondrial disease (autosomal recessive): Definitive.
mitochondrial disease (autosomal dominant): Disputed.
Homologues: Orthologues: chimpanzee SPG7 (92% identical), dog SPG7 (89% identical), mouse Spg7 (87% identical), rat Spg7 (86% identical), guinea pig SPG7 (86% identical), rabbit SPG7 (85% identical), pig SPG7 (85% identical), macaque SPG7 (82% identical), tropical clawed frog spg7 (75% identical), zebrafish spg7 (74% identical), Drosophila melanogaster Spg7 (49% identical), Caenorhabditis elegans ppgn-1 (43% identical), and 1 more. Paralogues in human: AFG3L2 (40% identical), YME1L1 (26% identical).
Diseases named in the same sentence as SPG7 in open-access papers:
SPG7 is named in the same sentence as 112 diseases in open-access papers, as found by Europe PMC text mining. Sharing a sentence is not in itself a finding about the gene and the disease. The quoted sentences say what the papers report.
Ataxia (53 papers, 2009 to 2026). Ataxia refers to impaired coordination of voluntary muscle movement. "Rare damaging SPG7 variants were detected in 58 patients with spastic paraplegia, ataxia, mitochondrial dysfunction, or motoneuron lesions." (PMID 39978794, 2025). "Cerebellar signs or atrophy on brain imaging are the most frequently observed additional features in complex SPG7-HSP patients, while SPG7 variants have been reported to be a common cause of undiagnosed ataxia." (PMID 41149856, 2025). "After identifying a large cohort of patients with various SPG7 variants, the phenotypic spectrum was broadened with ataxia, optic nerve impairment, and peripheral neuropathy." (PMID 39978794, 2025). "FAM124B has been proposed to be an important protein involved in neurodevelopmental disorders, while SPG7 mutations have been linked to spastic paraplegia and cerebellar ataxia." (PMID 40051167, 2025). "Of these, two had suspected multisystem atrophy (MSA-C) and seventeen underwent genetic screening appropriate to the presentation (one had a spinocerebellar ataxia 17 mutation and one was heterozygous for a pathogenic SPG7 mutation)." (PMID 39985693, 2025). "The SPG7 gene encodes a mitochondrial metalloprotease, and its dysfunction is a common cause of an adult form of recessive spastic paraplegia and cerebellar ataxias." (PMID 38239855, 2023). "Considering the atypical disease course (the patient walked without any support after 3 years), we carried out a genetic investigation for Ataxia, and a mutation in SPG7 was found." (PMID 34433436, 2021). "Our findings widen the spectrum of SPG7 mutations of ARHSP and indicate that the SPG7 mutation is an important cause of adult-onset undiagnosed ataxia." (PMID 30497413, 2018). "We recommend direct genetic testing for SPG7 mutations when cerebellar ataxia with dysarthria is associated with mild lower limb spasticity and a waddling gait." (PMID 30533525, 2018). "In particular, mutations in SPG7 have been implicated in cerebellar ataxia and progressive external ophthalmoplegia (PEO), and are responsible for 5–10% of HSP34." (PMID 29467464, 2018). "SPG7 mutation accounts for 1.5-7% of all the HSP but it is the cause of undiagnosed ataxia in 18.6% in a recent case series." (PMID 29057857, 2017). "For instance, ataxia is a major clinical presentation in patients with SPG7 mutations." (PMID 36441344, 2023). "Furthermore, the most common genotype that manifested initially with stiff leg (87.5%), ataxia (56.0%), and gait disturbance (45.9%) was SPG7; and onset presentation with cerebellar signs other than ataxia was more likely linked with SPG2 genotype (50.0%)." (PMID 36441344, 2023). "SPG7 mutations can cause both pure and complex phenotypes, especially later in the course of the disease, including cerebellar ataxia and atrophy, optic atrophy, chronic progressive external ophthalmoparesis, supranuclear palsy, cognitive impairment, thin corpus callosum, and polyneuropathy." (PMID 36139378, 2022). "SPG7 mutations result in mitochondrial dysfunction and may present with ataxia evolving to spastic ataxia phenotypes, as well as other features such as ophthalmoplegia and ptosis." (PMID 33646413, 2021). "Interestingly, the 2 patients with the lowest regional BPND in cerebellar gray matter both presented with ataxia (patient 1 with an SPG7 mutation and patient 8 with an MT-ATP6 mutation)." (PMID 33883237, 2021). "Indeed, recent studies demonstrated that SPG7 mutations are a frequent cause of undiagnosed cerebellar ataxias with adult-onset and pyramidal signs and provided the minimum prevalence of SPG7-related disease at 0.72/100,000." (PMID 33733696, 2021). "Although SPG7 primarily presents with a spastic paraplegia phenotype, it has also been identified as one of the most frequent causes of hereditary cerebellar ataxia, highlighting the phenotypic overlap between hereditary spastic paraplegias and cerebellar ataxias." (PMID 41596528, 2026).
Ataxia (continued). "Finally, the relatively low frequency of mutations in SPG7 might be related to their study in a concurrent “ataxia-associated” NGS panel." (PMID 30564185, 2018). "SGP7-associated HSP can present with a pure or complex phenotype, with SPG7 being the most common etiology in HSP patients with ataxia, found in 9.7% of cases." (PMID 41149856, 2025). "As such, genetic testing for SPG7 remains an important consideration in the work-up of spastic paraplegia, cerebellar signs or ataxia, and other neuro-ophthalmologic manifestations, including optic atrophy, cerebellar eye signs, and PEO." (PMID 41149856, 2025). "SPG7 is an autosomal recessive HSP characterized primarily by ataxia, which can be found in up to 57% of patients." (PMID 37648940, 2023). "HSP-MD with SPG7 had higher frequency of later onset during adulthood (82.9% vs. 8.5%), ataxia (OR = 12.6), extraocular movement disturbances (OR = 3.4) and seizure (OR = 3.7) compared to HSP-MD with SPG11." (PMID 36441344, 2023). "Parkinsonism should be carefully investigated, especially why in some disorders or specific genotype (e.g. SCAs, POLG-related ataxias, some PSEN1 mutations, SPG7) a good levodopa response has been reported." (PMID 37648940, 2023). "PRKCG, a gene known to cause a rare form of ataxia (SCA14), was also found to be common, as was SPG7, which had a similar high frequency." (PMID 34445196, 2021). "In a recent study, a patient with spastic paraplegia and ataxia was investigated with WES, revealing a novel missense variant in SPG7 (c.2195T>C; p.Leu732Pro) [94•]." (PMID 33646413, 2021). "Pathogenic variants in the SPG7 gene had been initially linked to pure and complicated HSP, whereas lately they have been considered as frequent causes of undiagnosed cerebellar ataxia and SA cases." (PMID 35096021, 2021). "Like SPG7, mutations in GBA2 and PNPLA6 can result in either spastic paraplegia or cerebellar ataxia with an autosomal recessive transmission mode." (PMID 33817696, 2021). "Aside from SPG7, there are other examples of overlap between cerebellar ataxia and spastic paraplegias." (PMID 33817696, 2021). "In line with our findings in ALS patients, ataxia was observed in 57% of HSP patients carrying mutations in the SPG7 gene, giving further evidence for cerebellar involvement as an SPG7 mutation-associated phenotypic feature." (PMID 32447552, 2020). "Recently, T2 hyperintensity of the dentate nucleus on brain MRI was reported in ataxia and HSP patients with biallelic SPG7 mutations." (PMID 32447552, 2020). "Variants in AFG3L2 produce dominant spinocerebellar ataxia and recessively inherited spastic-neuropathy syndrome (SCA28), while SPG7 induces recessive inherited spastic paraplegia." (PMID 33426505, 2020). "The third and last group (see cloud between the first and second group) includes SPG7 and appears to be characterized by the presence of muscle atrophy, neuropathy and ataxia." (PMID 27077743, 2016). "In SPG7, the occurrence of cerebellar ataxia and/or atrophy or progressive external ophthalmoplegia suggests that the analysis of this gene should be extended to other phenotypes." (PMID 25758904, 2015). "A genetic screening for ataxia covering nearly 50 genes (next generation sequencing panel) ruled out pathogenic mutations associated with spinocerebellar ataxia (SCA) as well as familial PAPT forms (POLG, GFAP, and SPG7)." (PMID 39450592, 2025). "As the symptoms worsened rapidly, a novel SACS mutation (c.4003 G>A, p.1335 Val>Ile, Heterozygous) was discovered using WES, although no pathogenic mutations with low frequency were found in ataxia-related genes, such as SPG7, FXN, and GFAP." (PMID 38132465, 2023). "SPG7 itself is considered to be a complicated form presenting with cerebellar ataxia." (PMID 36270162, 2022).
Ataxia (continued). "Finally, 13/39 sporadic patients with ataxia (33.3%) received a genetic diagnosis as follows: four with homozygous intron 1 expansion in FXN; three biallelic variants in SPG7, 2 CANVAS, 1 SACS, 1 SCA1, 1 SCA2; and one FXTAS." (PMID 33669240, 2021). "Certain genes are shared between HSP and ataxias, and SPG7 is the leading example." (PMID 33817696, 2021). "SPG7 accounted for 2.3% of cerebellar ataxia cases in an Italian population." (PMID 33646413, 2021). "The SPG7 gene with more than 100 reported pathogenic variants, was initially linked to pure and complicated HSP with cerebellar atrophy, and now represents a frequent cause of undiagnosed cerebellar ataxia and SA." (PMID 35096021, 2021). "SPG7 mutation should be remembered as an important cause of undiagnosed ataxia especially where next generation sequencing is not widely avaialbale or affordable." (PMID 29057857, 2017). "Likewise, although ataxia has been described as a presenting feature of SPG7, the absence of spasticity was thought to reduce the likelihood of a positive SPG7 result, moving this specific gene test down the priority list." (PMID 25497598, 2015). "Mice homozygous for Spg7 deletion, which in addition also bear the loss of function Afg3l2Emv66 mutation in one allele, display a more severe phenotype with an earlier onset of symptoms when compared with Spg7 null mice, and they also develop a marked cerebellar ataxia." (PMID 20426821, 2010). "Furthermore, as recently observed in ataxia linked to both ultra-rare (i.e., POLR3A) and relatively more common (i.e., SPG7) genes, the presence of deep intronic mutations (not usually sought in TRP studies) might also explain these difficulties." (PMID 34445196, 2021). "Indeed, while WGS did not detect candidate variants of interest in other HSP or ataxia genes, it revealed a novel heterozygous variant within intron 2 of the SPG7 gene, which was inherited from the mother." (PMID 31854126, 2020). "In addition, genes commonly associated with HSP, such as SPG7, were found to cause a predominant cerebellar ataxia phenotype in some patients lacking pyramidal signs." (PMID 32340215, 2020). "SPG7 (36.8%), SPG11 (20.4%), and SPG5 (6.3%) were the commonest genotypes among those manifesting with ataxia." (PMID 36441344, 2023). "In a Dutch cohort of 60 SPG7 patients, one patient presenting with HSP and ataxia syndrome was a compound heterozygous for p.Leu78* with another SPG7 mutation." (PMID 36139378, 2022). "For example, accumulation of EMRE protein in the absence of mitochondrial AAA-proteases AFG3L2 and SPG7, whose mutations are associated with spinocerebellar ataxia and hereditary spastic paraplegia, is responsible for mitochondrial Ca2+ overload and may contribute to neuronal loss." (PMID 32769116, 2020). "And autosomal recessive SPG such as SPG7 and SPG11 can also present with ataxia." (PMID 38035585, 2023). "Surprisingly, SPG7, which causes PMD trough impaired mtDNA maintenance, is not represented in our cohort despite ataxia and parkinsonism are commonly reported features." (PMID 34259909, 2022). "The most striking example is SPG7, which is responsible for HSP or cerebellar ataxia or both." (PMID 33817696, 2021). "Our results highlight this as SPG7 was not covered by one ataxia panel, SYNE1 by another, and ANO10 was not included in either panel." (PMID 25976027, 2015). "This did not include patients with SPG7 who were identified through their ataxic presentation and were included in the ataxia section above." (PMID 26341866, 2015). "Abnormalities of the nervous system, including neurodevelopmental abnormality (HP:0012759), ataxia (HP:0001251), seizure (HP:0001250), peripheral neuropathy (HP:0009830) etc., were present in 44% of the families reported, and the top five contributing genes were POLG, SPG7, MFN2, FXN and C19ORF12." (PMID 39423307, 2025).
Ataxia (continued). "Furthermore, several individuals without pyramidal symptoms had a major cerebellar ataxia phenotype caused by genes typically linked to HSP, such as spastic paraplegia 7 (SPG7; OMIM*607259)." (PMID 39336794, 2024). "Unsuccessful identification of causal variants by first-line clinical testing can stem from technical or bioinformatics issues, but in this case was simply due to the fact that SPG7 was not included on the selected ataxia and mitochondrial genes panel at the time of testing." (PMID 38239855, 2023).